CLBA1 (clathrin binding box of aftiphilin containing 1)
Synonyms: C14orf79
Tractability: No criterion of Open Targets' tractability assessment is met for any kind of drug.
Gene: Protein-coding gene on chromosome 14 (104,985,775 to 105,010,482, forward strand). Ensembl gene ENSG00000140104.
Subcellular location (Human Protein Atlas): Vesicles; Cytosol; Nucleoplasm
Gene Ontology:
Molecular function: clathrin binding
Cellular component: AP-1 adaptor complex; trans-Golgi network membrane
Genetic constraint (gnomAD): Loss-of-function variants: 30 observed, 30.52 expected, observed/expected ratio (o/e) 0.98, 90% interval 0.73 to 1.33. The upper end of that interval is the gene's LOEUF score, 1.33, which puts it in group 5 of 6, group 1 being the genes least tolerant of losing a copy. Missense variants: 451 observed, 431.09 expected, observed/expected ratio (o/e) 1.05, 90% interval 0.97 to 1.13. Synonymous variants: 160 observed, 160.48 expected, observed/expected ratio (o/e) 1, 90% interval 0.88 to 1.14.
Homologues: Orthologues: chimpanzee CLBA1 (99% identical), macaque CLBA1 (92% identical), mouse Clba1 (58% identical), rat Clba1 (58% identical), pig CLBA1 (55% identical), dog CLBA1 (38% identical), tropical clawed frog clba1 (18% identical), Caenorhabditis elegans Y45G5AM.9 (14% identical). Paralogues in human: AFTPH (20% identical).